CD4 (CD4 molecule)
Diseases named in the same sentence as CD4 in open-access papers (continued):
Sharing a sentence is not in itself a finding about the gene and the disease.
tumor (continued). "We analyzed the effect of therapy on the relative number (out of total CD45+ cells) of CD8+ T cells, CD4+ T cells, and NK cells at the tumor site." (PMID 39474427, 2024). "CCL5 expression by gastric cancer is correlated with tumor progression; a possible mechanism behind this association is the disproportional accumulation of CD4+ and CD8+ T cells, plus selective apoptosis of CD8+ T cells in the tumor." (PMID 38786066, 2024). "The inclusion of tumor-unrelated and tumor-specific CD4+ T cell helper antigens in the neoantigen vaccines increased not only the frequency of vaccine-induced CD8+ T cells, but also altered their surface phenotype." (PMID 39040850, 2024). "While direct CD4 T cell activation through pMHC-II on tumor cells can be effective in select settings, DCs are central to mediating CD4 help." (PMID 38903502, 2024). "In CRC, Foxp3+CD25+CD4+ Tregs inhibit anti-tumor immune responses in CRC patients and mediate immune evasion in CRC." (PMID 39262952, 2024). "While frequency of CD4 T cells was associated with better prognosis in HNSCC, the specific role of CD4 T cells in HNSCC anti-tumor immunity remain less well-understood." (PMID 39055715, 2024). "CD4+ T lymphocytes play a pivotal role in the regulation of the immune system and the promotion of anti-tumor responses." (PMID 39845973, 2024). "The abundance of these bacteria was correlated with a decrease in the number of tumor-infiltrating T cells positive for CD4, CD8, and CD45RO." (PMID 38242997, 2024). "Closely resembling human AITL disease, murine CD4+ tumor cells expressed Tfh markers (PD-1, CXCR5) as their human counterparts, which are often defined as Tfh-like cells." (PMID 38321568, 2024). "We adapted this protocol to profile the molecular kinetics of human CD4+ T-cell exhaustion, focusing on memory CD4+ T cells to minimize cellular heterogeneity, given their abundance and critical functions in the tumor microenvironment." (PMID 39689157, 2024). "PD-L1 IC and CPS ≥10% was more often detected in tumours with greater number of tumour-infiltrating CD4+Foxp3+ T cells (p = 0.01 and p = 0.025, respectively)." (PMID 38541208, 2024). "The uniHELP vaccine contained the same CD8+ T cell antigens combined with three universal, non-tumor-related CD4+ T cell antigens, including PADRE as well as TTFCp30-and HIV-nef-derived antigens." (PMID 39040850, 2024). "Conversely, CD4-positive T follicular helper (Tfh) cells are enriched in FL and generally support tumor growth in FL." (PMID 39456838, 2024). "Under the influence of tumor antigens encoded by BNT111, activated CD4+ T cells differentiate into Th1, Tfh and Treg cells, enhancing tumor eradication by secreting cytokines like IFN-γ and TNF." (PMID 39460333, 2024). "RLaSota-BC-RFP-treated tumors demonstrated significantly higher levels of tumor-infiltrating CD4+ (p = 0.008) and CD8+ (p = 0.0003) T lymphocytes compared to rLaSota-RFP- and PBS-treated groups in the B16F10 model." (PMID 39458338, 2024). "And there were more tumor cells surrounded CD4+Tregs (P = 0.005) and CD8+Tregs (P = 0.007) in TC than in IM." (PMID 39093404, 2024). "Tumor derived TGFβ plays an important role in this promotion of FoxP3 expressing Tregs from naïve CD4+ T cells." (PMID 38571964, 2024). "This approach achieved significant inhibition of tumor cell growth, which correlated with CD4 and CD8 T-cell infiltration within the tumors and the induction of systemic CTL responses." (PMID 39125578, 2024). "These dendritic cells, as vaccines, work as antigen-presenting cells (APCs) to stimulate an immune response against the tumor by activating the CD4 and CD8 T cells." (PMID 39201585, 2024). "The relevance of T cell immunity for the success of tumor-targeted therapy was proven by the depletion of CD8+ T cells or CD4+ T cells in our tumor model as their absence abrogated the efficacy of BRAFi treatment." (PMID 38631706, 2024).
tumor (continued). "Cluster A has a lower ICD score and better prognosis, as well as a higher proportion of anti-tumor immune cells such as CD4+ T cells, CD8+ T cells, NK cells, and dendritic cells, but it is also accompanied by the enrichment of more Tregs." (PMID 38627685, 2024). "NK cells can directly kill tumor cells and interact with other immune cells, such as DCs and CD4+ T cells, to promote the maturation of DCs or the differentiation of Th1 cells." (PMID 38791188, 2024). "Precise mechanistic studies have shown that CXCL17 is associated with increased intratumoral infiltration of MDSCs, TAMs, and Tregs that mediate tumor immunosuppression, while decreasing CD4+ and CD8+ T cells with antitumor properties." (PMID 37666495, 2024). "The CD4+/CD8+ ratio crucially determines tumor patients' cellular immune function, with an increased ratio indicating dominant positive immune response regulation, while a decreased or less than 1 ratio suggests impaired cellular immune function." (PMID 38685799, 2024). "Treatment with the inhibitors notably augmented T cell tumor infiltration, augmented the activation of CD8+ T cells via ATP, and induced the formation of tumor‐associated PD‐1+ TCF1+ CD8+ CD4+ stem‐like DPT cells." (PMID 39225354, 2024). "MHC-II is mainly expressed by specialized antigen-presenting cells, such as DCs, B cells, and macrophages, as well as some tumor cells, and primarily presents exogenous peptide antigens to CD4+ T cells." (PMID 39263534, 2024). "In recent years, more and more attention has been paid to the role of CD4+T cells in anti-tumor immunity and the mechanism involved in tumor immune escape.CD4+T cells, like macrophages, are a highly heterogeneous cell population." (PMID 38279145, 2024). "The earliest neoepitopes were identified as those recognized by tumor-specific CD4+ or CD8+ T cells." (PMID 38426497, 2024). "On the other side, MHC-II molecules, the restricting element for CD4+ TH cell recognition, were detected in a relevant amount of tumor cells (at least 10%) only in 10 patients of the recruited population (i.e., 43.5%)." (PMID 39035008, 2024). "Sakaguchi’s main focus was on therapeutic immunity, either through adoptive tumor-primed CD4+ T-cells or by examining the ratio of CD8+ lymphocytes to tumor-infiltrating cells." (PMID 39664195, 2024). "In our study, the infiltrated levels of CD4+ T_C2, B_C3, and Mac_C3 in tumor samples were significantly higher than in normal samples." (PMID 38918785, 2024). "Salmonella flagellin has also been implicated in the reductions of CD4 + CD25+ T cells through TLR5 in the tumor microenvironment and the induction of PD-L1 expression in dendritic cells and CD4+ cells." (PMID 39594765, 2024). "FCM demonstrated that there were more CD155 tumour cells and CD4 + CD25 + Treg cells showed increased TIGIT levels." (PMID 38867002, 2024). "ICT- and neo VAX-induced tumor rejection was dependent on both CD4 and CD8 T cells, as mAb depletion of either T cell subset abolished therapeutic efficacy." (PMID 38187708, 2024). "IL4 and IL4R expression was higher in Tfh tumor cells in the RR group, whereas IL‐4+/CD4+ cells and IL‐4R+/CD20+ cells showed cell communication." (PMID 38145335, 2024). "Beyond the extensively studied CD8+ T cell compartment, CD4+ T cells, non‐T immune cells, and tumor cells also show numerical and/or functional changes after PD‐1/PD‐L1 blockade, implying their roles as potential responders of PD‐1/PD‐L1 blockade." (PMID 39248327, 2024). "Specifically, we discovered that fucosylation of tumor-expressed MHC-II protein HLA-DRB1 triggers CD4+T cell-mediated induction of tumor-infiltrating immune cells and tumor suppression." (PMID 38646527, 2024). "Dendritic cells (DCs) migrate from the tumor site to the SLOs, wherein major histocompatibility complex molecule-peptide complexes are presented to CD4+ T and CD8+ T cells by mature DCs." (PMID 38416737, 2024).
tumor (continued). "Evaluation of TDLNs following IT CXCL9/10-DC therapy in KPL-3M tumor-bearing mice showed enhanced proliferation of both CD4+ and CD8+ T cells, ascertained by Ki67+ staining, and an increased T cell effector polarization, determined by CXCR3 expression." (PMID 38518770, 2024). "GPX4 deficiency in T cells significantly accelerated tumor growth and mitigated the accumulation and function of CD8+ T cells accompanying decreased infiltration of total CD4+ T cells and CD4+Foxp3+ regulatory T cells in comparison with the control mice." (PMID 38441967, 2024). "On the other hand, immune cells besides CD8 T cells, such as CD4 T cells, also contributed to tumor eradication since ~40% of CD8-KO recipient mice did eradicate tumor." (PMID 39055715, 2024). "Cytotoxic T lymphocytes and natural Killer (NK) cells display anti-tumor response, while M2 macrophages, Tregs, and CD4 + T helper (Th)-17 cells exert tumor-promoting activities." (PMID 38741166, 2024). "Findings revealed that DCLEX-TGF-β1si significantly boosted CD4+ T-cell proliferation, promoted Th1 cytokine secretion, and induced a robust tumor-specific cytotoxic T lymphocyte (CTL) response in vitro." (PMID 39572459, 2024). "Immunohistochemistry study showed reduced infiltration of FoxP3+ Treg cells and increased numbers of CD4+ T-cells and cells expressing interleukin-12-beta-2 receptor (IL-12Rβ2+) and interleukin-24 (IL-24+) in the tumour from γT3-treated animals." (PMID 39416707, 2024). "For example, RT promotes the release of tumor-associated antigens, which, once processed by antigen-presenting cells (APCs), prime CD8+ and CD4+ T cells in the draining lymph nodes." (PMID 38779678, 2024). "Previous studies have shown that CD4+ T cells play an important role in directly eliminating tumours or indirectly providing support for the tumour-killing function of CD8+ T cells." (PMID 38698811, 2024). "CD4+ T cells can target tumor cells through various mechanisms, either by directly eliminating tumor cells through cytotoxicity or by indirectly eliminating tumor cells by regulating the tumor microenvironment." (PMID 38957470, 2024). "Results showed high CD47 expression on 45.6% ± 5.31% of CD4+ and 53.5% ± 7.51% of CD8+ lymphocytes in adjacent tissues, whereas in tumor tissues, CD47high+ lymphocytes decreased to 26.7% ± 4.16% for CD4+ and 37.7% ± 7.21% for CD8+." (PMID 39652550, 2024). "CD20+ TIBs and CD4+ T cells were predominantly located within the tumor stroma (yellow dotted line)." (PMID 39594720, 2024). "ATRX loss led to a significant increase in CD3 + T cells and, in particular, CD4 + T-cells within tumor-bearing hemispheres in allografted mice, while macrophage infiltration was reduced." (PMID 38272925, 2024). "We observed that ELP treatment activated CD4+ and CD8+ T cells, reduced the expression of M2 type tumor-associated macrophages (TAMs), polarized TAMs towards the M1 type, and decreased regulatory T cells (Tregs)." (PMID 38612457, 2024). "MHC-II molecules, which are required for the CD4+ T cell response and tumor suppression, were expressed by both of these cell types." (PMID 38391974, 2024). "In the PANC02 cell-derived tumor model, there was an increase in infiltration of CD4 + T cells in the CXCR2 CAR-T group." (PMID 38430267, 2024). "Analysis of Treg cells in the CRC tumor site demonstrated two main phenotypes: CD4+FOXP3hiCD45RA− and CD4+FOXP3loCD45RA−." (PMID 38690280, 2024). "The primary function of CD4+ T cells includes facilitating anti-tumor immunity through various mechanisms." (PMID 39507526, 2024). "This vaccine elicited auto-antibodies against MMP-2, with CD4+ T cells identified as pivotal in driving the anti-tumor response." (PMID 39081320, 2024). "With the TME-Analyzer, we indeed observed higher densities of B cells, CD4 T cells, CD8 T cells and tumor associated macrophages (TAMs) in the center of inflamed but not non-inflamed tumors, being in line with previous reports using Mx-IF and IHC imaging." (PMID 40604303, 2024).
tumor (continued). "An enriched IFN-I signature, which included both IFN-I response-related and IFN-I production-related genes, was identified in tumor-infiltrating effector (memory) CD4+ T cells." (PMID 38383773, 2024). "DFNB59 expression was significantly and positively correlated with the tumor purity and the degree of infiltration of CD4+ T cells." (PMID 38434972, 2024). "Decreased TNF-α and IFN-γ expression was observed in adoptively transferred tumor-infiltrating CD8+ T cells in Rag1−/− mice challenged with Id2fl/flCd4-Cre+ CD8+ T cells plus Id2fl/flCd4-Cre− CD4+ T cells." (PMID 38287103, 2024). "The reduced levels of glucose within the TME force the neutrophils to use mitochondrial-derived NADHP for ROS production, which then inhibits the CD4+ T cells and has been shown using a 4T1 tumor-bearing mice model." (PMID 38474175, 2024). "Intriguingly, RSL3 encapsulated in the ROS‐responsive hydrogel exerts antitumor effects by increasing the numbers of tumor‐infiltrated CD4+ T cells, CD8+ T cells, and M1 macrophages while reducing the number of M2 macrophages." (PMID 39308160, 2024). "Chemotherapy can trigger the release of the chemokine CXCL10 and the rapid secretion of type I IFNs, which can recruit CD8 + and CD4 + effector T cells to tumor sites and boost antitumor immunity." (PMID 38549044, 2024). "The response to anti-checkpoint blockade therapy can be influenced by tumor-infiltrating immune cells, and upregulation of some immunological checkpoint genes, such as PD-1 and CTLA-4, can be due to tumor-infiltrating CD4+ T cells." (PMID 38356712, 2024). "Subsequently, using the CIBERSORT algorithm, we found positive correlations between GLYAT expression and mast cells resting, monocytes, macrophages M2, macrophages M1, T cell CD4 naive and NK cells activated in the tumour immune microenvironment." (PMID 39495775, 2024). "Co‐localization of the proliferation marker Ki67 revealed a strong proliferative activity for invading anti‐tumor CD4 T cells, CD8 T cells, and NK cells." (PMID 39297408, 2024). "Based on these observations we conclude that INHBA(+) fibroblasts play a role in shaping the tumor immunosuppressive microenvironment by inducing expansion of the pro-tumorigenic CD4( +) CD25(+) FOXP3(+) Tregs." (PMID 38360876, 2024). "We first examined CD4+ and CD8+ T cells in the tumor and spleen on Day 8 post‐irradiation, and representative gating for CD4+ and CD8+ tumor‐infiltrating lymphocytes (TIL) was shown." (PMID 38379323, 2024). "HLA-A*11:01–restricted TCR-engineered CD8+ and CD4+ T cells exhibited lytic activity against KRASG12V+ tumor cell lines with low-abundance neoantigen expression." (PMID 39287991, 2024). "For example, cancer cell-derived exosomes engineered with tumor-associated antigens can inhibit M2 tumor-associated macrophages and myeloid-derived suppressor cells (MDSCs), while increasing CD8- and CD4-positive T cells." (PMID 38655063, 2024). "The serum copper level significantly correlated with the percentage of CD3+CD69+, CD4+PD-1 and CD8+PD-1 in tumor samples and CD4+PD-1, CD8+PD-1 in node samples." (PMID 38256645, 2024). "We also found that tumor regression mediated by zebularine was, at least in part, dependent on the co-presence of CD4+ and CD8+ T cells." (PMID 38755254, 2024). "These conditions were extensively studied in preclinical research which provided a description of the complex modulation of the CD8+ anti-tumor response involving the immunosuppressive activity of CD4+ and FOXP3 lymphocytes." (PMID 38638854, 2024). "DCs are spatially located at tumor margins, and after depleting DCs, CD4+ T cells in PDAC differentiate into Th17 cells, which secrete more IL-17 and promote tumor growth and metastasis." (PMID 38982491, 2024). "We found that in Ctrl and Mg‐OPSZ tumors, CAFs formed tumor capsules and were widely distributed in the inner part, excluded CD4+ T cells from efficiently infiltration." (PMID 38757665, 2024).
tumor (continued). "The densities of regulatory T cells (Treg; CD3+CD4+FoxP3+ cell) were significantly decreased and almost disappeared in the tumor microenvironment of posttreatment tissue compared with pretreatment tissue." (PMID 38228697, 2024). "PD-L1 and tumor microenvironment (CD4, CD8, CD68 and CD163) expression were investigated in LSCC using immunohistochemistry." (PMID 39123373, 2024). "CD4+ Th1 cells orchestrate tumor killing by stimulating the production of major histocompatibility complex (MHC) class II on tumor cells, facilitating the accumulation of innate and adaptive immune cells with enhanced cytotoxicity function." (PMID 38827732, 2024). "Relevant immune cells include tumor‐suppressive CD4+ T cells, CD8+ T cells, M1 macrophages, immunosuppressive M2 macrophages, and Tregs." (PMID 39308160, 2024). "Tregs, constituting another specific population of CD4+ T cells, are often correlated with poor prognosis and tumour progression." (PMID 38468489, 2024). "In contrast, the number of tumor cells reduced significantly when HVEM+ K562 cells were treated with the HVEM blocker before being co-cultured with CFSE CD4+ T cells (left column)." (PMID 38785930, 2024). "Tumor endothelial cells induce immunosuppressive CD4+ T cells through IL-10 and TGFβ, contributing to tumor evasion." (PMID 39325128, 2024). "Conversely, one study indicated that CD4+ T cell infiltration was notably higher at the center of the tumor than at its edge." (PMID 39845973, 2024). "Treatment with AgNPs-G decreased the percentage of CD4+ cells and regulatory T cells in tumor tissue." (PMID 39126001, 2024). "Elevated LAG3 expression strongly correlates with the infiltration levels of CD4 memory activated T cells, resting NK cells, M0 macrophages, M1 macrophages, and mast cells in the tumor microenvironment." (PMID 39199429, 2024). "Tumor-infiltrating lymphocytes, particularly CD8+ cytotoxic T cells, and the balance between CD8+ and CD4+/forkhead box P3+ regulatory T cells in the tumor microenvironment have emerged as critical factors." (PMID 38541669, 2024). "This led to an increase in the number of macrophages, CD4+ T cells, the proportion of CD4+ T cells, and M1 macrophages as well as inhibition of angiogenesis in the tumor microenvironment." (PMID 39367471, 2024). "Paradoxically, however, MHC-II neoantigen presentation on tumor cells can also inhibit antitumor effects, possibly by inducing neoantigen-reactive regulatory CD4+ T cells in the tumor microenvironment." (PMID 39569190, 2024). "In the past, the tumor‐infiltrating CD4+ T cells were examined using numerous approaches of prognostic indicator analyses." (PMID 39248131, 2024). "The infiltration of different types of immune cells (such as CD8+ T cells, CD4+ T cells, and natural killer cells) in tumor tissues can be quantitatively analyzed via immunohistochemical staining, flow cytometry, and other techniques." (PMID 39194667, 2024). "To validate these observations, we assessed the levels of the corresponding proteins in tumour-specific CD4+ TILs and splenocyte populations from mice treated with T3-HDVax, T3-LDVax or PBS." (PMID 39048822, 2024). "Tregs characterized by FOXP3+ CD25+ CD4+ expression promote tumor immune evasion by suppressing the immune responses of CD8+ and CD4+ T cells." (PMID 39263534, 2024).